PPARG (peroxisome proliferator activated receptor gamma)
Diseases named in the same sentence as PPARG in open-access papers (continued):
Sharing a sentence is not in itself a finding about the gene and the disease.
colitis (continued). "Thiazolidinedione (TZD) agents, such as rosiglitazone, are PPARγ agonist ligands shown previously to ameliorate DSS-induced colitis in mice (139, 150, –, 154) and 2,4,6-trinitrobenzene sulfonic acid (TNBS)-induced colitis in rats." (PMID 37768050, 2023). "The increased IL-1b and TNF serum levels and enhanced HIF-1 and IL-10 expression in colitis mice were suppressed by CYN therapy, and the treatment facilitated IL-4, CCL2, and PPARγ expression." (PMID 36278202, 2022). "To explore the potential molecular mechanism of COS in alleviating colitis, we tested the effect of COS on PPARγ/SIRT1 and NF-κB signaling pathway in LPS-stimulated RAW 264.7 cells and in the colonic tissues of DSS-induced colitis mice." (PMID 35200626, 2022). "For example, Bergenin restrained the activation of macrophages by modulating the PPARγ/SIRT1/NF‐κB‐p65 pathway, thereby ameliorating DSS‐triggered colitis in mice." (PMID 35524480, 2022). "Therefore, COS may prevent or treat colitis by suppressing the production of inflammatory factors, preventing the inflammation response via activating PPARγ and SIRT1, inhibiting the acetylation and phosphorylation of NF-κB p65, and optimizing the intestinal microbiota composition." (PMID 35200626, 2022). "Our previous research has revealed that a natural PPARγ agonist, madecassic acid, can up-regulate the level of CD36 as well as the frequency of Treg cells in dextran sulfate sodium (DSS)-induced colitis mice." (PMID 35392915, 2022). "Defect of IGF2BP2 promoted M1 response, leading to enhancing DSS induced experimental colitis development, but impaired M2 activation through stabilizing TSC1 and PPARγ mRNA." (PMID 34258163, 2021). "Mechanistically, LEP treatment was found to block the activation of PPARγ/NF-κB and STAT3 pathways by upregulating PPARγ expression and retarding the phosphorylation of NF-κB p65, IκB, and STAT3 in DSS-induced colitis." (PMID 33981232, 2021). "MA is able to inhibit the activation of γδT17 cells through PPARγ–PTEN/Akt/GSK3β/NFAT pathway, reduce the level of IL-17 in colon tissues of colitis mice, and ameliorate DSS-induced colitis in mice." (PMID 32929062, 2020). "In summary, these findings reveal that MA inhibits the activation of γδT17 cells through PPARγ–PTEN/Akt/GSK3β/NFAT pathway, which contributes to the amelioration of colitis." (PMID 32929062, 2020). "The correlation between activation of PPARγ, decrease in γδT17 cell number, and amelioration of colitis by MA was validated in mice with DSS-induced colitis." (PMID 32929062, 2020). "They reported the first dual activation of PGD2 receptor (DP1) and PPARγ by PGD2-G and its anti-inflammatory properties in a murine model of colitis." (PMID 32536865, 2020). "Especially the RXR/PPARγ heterodimers, which are permissive to activation by both PPARγ and RXR ligands, have been investigated in colitis models." (PMID 31139192, 2019). "They suggested that there is interference between PPARγ and TLR-4 signaling pathways in a sense that PPARγ can significantly prevent colitis by reducing NF-κB activity." (PMID 31011554, 2019). "Other studies have shown that engagement of PPARγ-mediated signaling by its agonists such as rosiglitazone attenuated the severity of inflammatory lesions in both experimental and spontaneous models of colitis and might be effective in patients with ulcerative colitis." (PMID 25969456, 2016). "TLR and interleukin activation, PPARγ-inhibition and regulation of PRNP (PrPc), occurs in both TNBS-colitis and IBD." (PMID 23382912, 2013). "Deletion of PPARγ in CD4+ T cells impaired mucosal iTreg and enhanced colitogenic Th17 responses in mice with CD4+ T cell-induced colitis." (PMID 23592971, 2013). "Up-regulated genes in both TNBS-colitis and human IBD included ADA, PrPc, and IL-1α, while down-regulated genes consisted of aldehyde dehydrogenase 1 family, member A1 (ALDH1A1), and PPARγ." (PMID 23382912, 2013).
colitis (continued). "The therapeutic value of PPARγ activation in CDAD was further demonstrated by the significant amelioration of CDAD and suppression of colitis in mice treated with pioglitazone, a full PPAR γ agonist." (PMID 23071818, 2012). "Gene expression analysis indicated a decrease of PPARα, PPARγ and NAAA, and an increase of FAAH and iNOS in the active colitis mucosa." (PMID 22662201, 2012). "Similarly, activation of PPARγ can suppress experimentally induced colitis which could also reduce plasma cytokine levels, and in fact several clinical trials of PPARγ agonists for treating colitis are in progress." (PMID 17207275, 2007). "Compared with normal colon tissue, PPARγ gene is markedly down-regulated in the colon tissue of patients with active colitis and nonactive colitis." (PMID 40948937, 2025). "Rosiglitazone (ROSI), a PPARγ agonist known to attenuate macrophage inflammatory responses, is encapsulated into Effero‐RLP as model drug to regulate macrophage functions in DSS‐induced colitis mouse model." (PMID 38790144, 2024). "In a murine AOM/DSS-induced colitis model with +/-5-ASA treatment, PPARγ expression was significantly downregulated in the case of AOM/DSS-induced colitis without 5-ASA treatment compared to healthy controls." (PMID 39451206, 2024). "We found that the PPARγ‐target gene CD36 is upregulated during DSS‐induced colitis on ATMs in wild‐type mice and but not in ATMs from Atg7Ad mice." (PMID 36795015, 2023). "Another published paper has reported that, by preventing the degradation of PPARγ, the expression of CD36 can be enhanced, while the Th17/Treg balance can be restored in mice with colitis, implying the involvement of fatty acid oxidation (FAO) in the effects of PPARγ on Treg responses in vivo." (PMID 35392915, 2022). "In addition, magnolol restrained the expression of TNF-α, IL-1β, and IL-12 via the regulation of NF-κB and peroxisome proliferator-activated receptor-gamma (PPAR-gamma) pathways and played protective effects on DSS-induced colitis." (PMID 34159200, 2021). "Furthermore, exogenous treatment with inosine activated colonic PPARγ signaling and protected against DSS-induced colitis through improving mucosal barrier functions." (PMID 33820558, 2021). "The results were similar to those obtained from the colitis model, as GLS1 overexpression effectively dampened the restriction of PPARγ agonists on the level of 2-HG as well as H3K4me3 in the lungs, and the regulation of the levels of GSH and ROS in lymphocytes in the lungs." (PMID 33754076, 2021). "To determine whether PPARγ signaling activation was required for the impacts of BL on colitis protection, we examined colitis symptoms in the DSS-induced colitis model." (PMID 33820558, 2021). "One study showed that dual activation of PPARδ and PPARγ using conjugated linoleic acid (CLA) downregulated both TNFα and NFκβ activation while upregulating TGF-β1 as well as protecting against DSS and CD4 induced colitis in mice." (PMID 35003101, 2021). "This is in accordance with other authors who also reported PPARγ levels suffer little to no variances in colon tissue throughout the development of DSS colitis." (PMID 33519451, 2020). "The protective effect of conjugated linoleic acid (CLA) against IBD has been shown in vitro and in vivo to be mediated through PPARγ activation, although other n-PUFAs may antagonize the effects of CLA on PPARγ in experimental colitis." (PMID 33603741, 2020). "In another study, geraniol improved experimental colitis partly via its antioxidant, anti-inflammatory, and immunosuppressive potentials, possibly by modulating the Wnt/GSK-3β/β-catenin, p38MAPK, NF-κB, and PPARγ signaling pathways." (PMID 33053761, 2020). "In terms of the activation/expression of receptors and signaling pathways in response to C. glabrata sensing and colitis, MBL-C and Myd88 expression increased significantly, while the expression of TLR-4 and PPARγ decreased in the colons in response to C. glabrata ΔChs3." (PMID 29463799, 2018).
colitis (continued). "Chitin treatment increased chitinase-3-like protein-1, enabling chitin digestion and the generation of small sized chitin particles that induced IL-10 production via PPARg, NOD-2, and TLR-8 sensing, promoting the attenuation of colitis and C. glabrata elimination." (PMID 29463799, 2018). "The correlation between activation of PPARγ and AMPK, downregulation of ACC1 expression, restoration of Th17/Treg balance and attenuation of colitis by madecassic acid was validated in mice with DSS-induced colitis." (PMID 28358365, 2017). "Finally, to confirm the key role that PPARγ played in bergenin-mediated protection of colitis, the model of DSS-induced colitis was established in mice, bergenin was combined with GW9662, and 5-ASA and rosiglitazone were taken as positive drugs." (PMID 29375382, 2017). "PPARγ-deficient Treg cells did not suppress effector T cell responses or colitis development in one study, while another found that PPARγ was required for the development of colitis in lymphopenic conditions due to the increase of cell death without PPARγ." (PMID 27548145, 2016). "Although we initially observed that the absence of PPARγ led to increased colitis severity, in sharp contrast we also detected a simultaneous elevated innate immune response that seemed to serve a protective role." (PMID 24465207, 2014). "PPARγ and δ are recognized as central inhibitors of intestinal inflammation in DSS colitis." (PMID 23737845, 2013). "We previously investigated the modifying effects of PPARγ or α ligands (troglitazone, pioglitazone, orbezafibrate) on early phase of colon carcinogenesis with or without colitis inmale F344 rats." (PMID 18483618, 2008). "Of importance, thiazolidinediones still improve colitis severity incolonic epithelium-specific PPARγ−/− mice,but not in macrophage-specific PPARγ−/− mice,suggesting that macrophages are the relevant targets of these compounds in thisdisease." (PMID 18615187, 2008). "Treg cells lacking PPARγ are unable to suppress colitis in a regulatory Tcell-dependent model of inflammatory bowel disease, arguing that PPARγ is required forsuppressive regulatory function." (PMID 18509498, 2008). "Inaddition, PPARγ−/− macrophagerecruitment to inflammatory sites is increased, and these macrophages overreactto inflammatory stimuli, resulting in increased severity of DSS-induced colitis." (PMID 18615187, 2008). "By contrast with this result for PPARα knockout mice, at least one response to CLA depends on expression of PPARγ: the beneficial effect of CLA in a mouse model of colitis was absent in mice that lacked PPARγ in the colon." (PMID 15642120, 2005). "Moreover, intake of low dose sucrose (7.5 mg/ml) is found to activate PPARγ via restoring microbial dysfunction and upregulating SCFAs levels, thereby suppressing MAPK/NF-κB signaling pathway, while high dose sucrose (30 mg/ml) exacerbates DSS-induced colitis." (PMID 38699583, 2024). "Based on prior studies with single agonists in cell-specific KO mice and the phenotypes observed in our animal models, single PPARγ agonism appears sufficient to protect the epithelium in chemical-induced colitis (dual agonism did not offer additional advantage)." (PMID 35288651, 2022). "The PPARγ agonists rosiglitazone and pioglitazone were recently found to reduce the levels of 2-HG and H3K4me3 in the colon of mice with colitis and to regulate GSH and ROS levels in lamina propria lymphocytes by modulating GLS1/2-HG/H3K4me3 signaling in mouse models of colitis and asthma." (PMID 36211442, 2022). ", Butyrate can upregulate the expression of PPARG while downregulating the expression of HDACs, which indicated that butyric acid may play an important role in the synergistic effects of 5-ASA and SAHA in the treatment of experimental colitis." (PMID 34093178, 2021).
colitis (continued). "Given the crucial role of metabolites in regulating protein function, we wondered whether butyric acid is upstream of PPARG and HDACs, which may contribute to the synergistic effects of the combination of 5-ASA and SAHA in the treatment of experimental colitis." (PMID 34093178, 2021). "However, rosiglitazone may function through a PPARγ-independent pathway to suppress IL-6, TNF-α, and IL-1β production, as rosiglitazone administration attenuates colitis in IEC-specific PPARγ KO mice." (PMID 30804707, 2019). "The loss of PPARγ in immune cells impaired the ability of PUA to ameliorate experimental colitis, strongly suggesting that PUA could modulate mucosal immune responses and therefore ameliorate gut inflammation through a PPARγ-dependent mechanism, which antagonizes NF-κB, STAT and AP-1." (PMID 26714018, 2015). "Recent studies have reported that PPARγ plays an important immunoregulatory function in autoimmune diseases, such as experimental autoimmune encephalomyelitis (EAE), allergic airway inflammation, trinitrobenzene sulfonic acid-induced colitis, and insulin resistance." (PMID 25383620, 2014). "Likewise, little is known about the role of dendritic and T-cellspecific expression of PPARγ in colitis, as PPARγ knockout animals currently do not existfor these cell types." (PMID 18615192, 2008). "Additionally, oral administration of chitin in the DSS-induced colitis model reduced the number of aerobic bacteria and proliferation of C. glabrata, and decreased the impact of colitis mediated by the expression of TLR-8, dectin-1 and PPARγ and anti-inflammatory mediators." (PMID 35630457, 2022). "In colonic epithelium of UC patients, PPARγ expression was down-regulated; PPARγ agonist rosiglitazone could treat moderate UC; 5-aminosalicylic acid (5-ASA), a traditional UC therapeutic drug, ameliorated the symptoms of wild-type colitis mice, but was ineffective in PPARγ+/- heterozygous mice." (PMID 29375382, 2017). "Here, we uncovered a novel mechanism whereby S. Typhimurium inhibits the expression of the transcription factor PPARγ in the host intestine, surprisingly without TLR-4 involvement; this inhibition worsened the severity of the host's colitis." (PMID 24465207, 2014).
Hyperglycemia (186 papers, 2007 to 2026). An increased concentration of glucose in the blood. "The upregulation of PPARG cannot only redirect sugar metabolism but also alleviate the inflammatory response within the body, thereby reducing the damage caused by hyperglycaemia." (PMID 40417668, 2025). "The activation of PPARγ by honokiol is also associated with its effects on preventing against hyperglycemia and CVD." (PMID 38699583, 2024). "BBR attenuated hyperglycemia and its associated oxidative stress and inflammation through, possibly, the potentiation of the antioxidant defenses and upregulation of PPARγ expression." (PMID 32132921, 2020). "The severe hyperglycemia presented in the individuals undergoing dominant-negative mutations in the PPARγ gene have already confirmed a genetic link between PPARγ and T2DM." (PMID 31547097, 2019). "Thus, the downregulation of PPARγ inhibits blood glucose and lipid clearance, thereby causing hyperglycemia and hyperlipidemia." (PMID 32714390, 2020). "Another study used a pancreatic-specific PPARγ KO model generated by crossing mice with floxed PPARγ to mice with pdx-1 promoter driven Cre recombinase and showed that loss of PPARγ in the whole pancreas results normal size of β-cell islets, but hyperglycemia and impaired insulin secretion." (PMID 27483259, 2016). "Phenolic compounds extracted from R. dentatus were found to improve hyperglycemia by regulating carbohydrate metabolism in the liver, reducing oxidative stress, and upregulating PPARγ expression in diabetic rats." (PMID 41426507, 2025). "Hyperglycemia also upregulates PPARγ expression of BMMSC, thus inhibiting RUNX2 expression and promoting adipogenesis." (PMID 40873948, 2025). "miR-27a expression is stimulated by hyperglycemia, suppressing PPARγ and activating β-catenin, leading to podocyte injury and renal dysfunction in diabetic rats." (PMID 41009556, 2025). "Activation of PPARγ requires ligands, which include natural physiological molecules such as fatty acids and pharmacological agents to treat hyperglycemia and insulin resistance." (PMID 41407819, 2025). "Oleanolic acid, a pentacyclic triterpenoid, and (E)-β-caryophyllene, a bicyclic sesquiterpene hydrocarbon, act as dual activator of PPARα and PPARγ, decreasing hyperglycemia and lipid accumulation." (PMID 38699583, 2024). "Rosiglitazone (RSG) is a peroxisome proliferator-activated receptor-gamma agonist that reduces hyperglycemia and hyperinsulinemia and improves insulin signaling." (PMID 37508471, 2023). "Knockout of liver PPARγ reduced liver steatosis, but elevated blood triglycerides and free fatty acids in addition to exacerbating hyperglycemia and insulin resistance." (PMID 36836874, 2023). "To reveal the mechanism by which metformin affects hyperglycaemia-induced osteoporosis, we treat a mouse osteoporosis cell model with metformin and find that osteoblast mineralization increases and PPARγ expression decreases." (PMID 36951483, 2023). "We also induced PPARγ overexpression in osteoblasts and found that PPARγ overexpression reduced the antagonistic effect of metformin on aberrant gene expression induced by hyperglycaemia in osteoblasts." (PMID 36951483, 2023). "Previous experiments confirmed that the pathway by which metformin protects against hyperglycaemia in osteoblasts is related to a reduction in PPARγ." (PMID 36951483, 2023). "It should be noted that PPARγ has received a substantial attention owing to its effect on reducing hyperglycemia by increasing insulin sensitivity and decreasing hepatic glucose production." (PMID 37710214, 2023). "Another study suggested that chitosan prevents hyperglycemia by inhibiting intestinal glucose digestion and helps in transporting and enhancing glucose uptake, at least in part, by upregulating PPARγ expression of adiponectin in adipocytes." (PMID 35237941, 2023).